TNF (tumor necrosis factor)
Diseases named in the same sentence as TNF in open-access papers (continued):
Sharing a sentence is not in itself a finding about the gene and the disease.
Insulin resistance (continued). "Over expression of TNF causes insulin resistance through the inhibition of PI3K-mediated activation of insulin receptor substrate 1 (IRS-1) and insulin receptor substrate 2 (IRS-2), and tyrosine phosphorylation of the mitogen-activated protein kinases p42MAPK and p44MAPK." (PMID 22451839, 2012). "This investigation tests the hypothesis that expressions of TLR2 or TLR4 on monocytes and related inflammatory cytokines, such as TNF-α and IL-6, might be associated with insulin resistance in patients with RA." (PMID 23213270, 2012). "Antioxidants also partially prevented cellular insulin resistance caused by tumor necrosis factor-alpha (TNFα), glucocorticoids, and the saturated fatty acid palmitic acid, suggesting that oxidative stress plays a key role in their action on glucose metabolism." (PMID 24764512, 2012). "We tested whether FTox-G50 caused insulin resistance in skeletal muscle and whether anti-TNFα treatment could prevent any such effect." (PMID 22816003, 2012). "Since the role of TNF-α in inducing insulin-resistance in obese animals is now well-known we hypothesised that CL-induced improvement in insulin-resistance might be associated with the suppression of TNF-α mRNA expression in adipose tissue." (PMID 23056223, 2012). "Insulin resistance is associated with a state of chronic low-grade inflammation, and mediators such as tumor necrosis factor-α (TNF-α), interleukin 1beta (IL-1β), and interleukin-6 (IL-6) have been identified as being involved in metabolic control and impairment in insulin-receptor signaling." (PMID 22927832, 2012). "Based on our findings of improved insulin resistance in patients with active RA following treatment with anti-TNF agents, we examined whether this effect is associated with altered IRS-1 phosphorylation." (PMID 22691241, 2012). "Interestingly, TNFα activity is linked to insulin resistance, and many of these events are mediated in part by the pathways associated with extracellular signal-regulated kinases (ERK), c-jun N-terminal kinases (JNK) and nuclear factor kappa-B (NFκB)." (PMID 22093181, 2011). "TNFα is one of the inflammatory cytokines directly causing hepatic insulin resistance." (PMID 22076142, 2011). "TNFα, overexpressed in tissues of diabetic patients, has been implicated in insulin resistance." (PMID 21679392, 2011). "Insulin resistance may aggravate gradually in those Japanese subjects together with metabolic changes, such as hyperglycemia and dyslipidemia, on the presence of the TNF 308 G/A polymorphism." (PMID 21494616, 2011). "Moreover, visceral fat cells release some agents to the blood (e.g. plasminogen activator inhibitor-1, interleukin-6 and tumor necrosis factor-α) that are possibly linked to some aspects of insulin resistance." (PMID 20529329, 2010). "The observation here that increases in intestinal TNF-α precede but strongly correlate with weight gain, body fat, and subsequent development of insulin resistance, supports a potential role of intestinal derived TNF-α in the development of DIO and associated insulin resistance." (PMID 20808947, 2010). "Plasma levels of pro inflammatory cytokines like tumor necrosis factor- alpha are increased in acute alcoholic hepatitis and such cytokines induce insulin resistance and glucose intolerance which could consequently cause type II Diabetes mellitus." (PMID 19619316, 2009). "TNF−α is one of the candidate molecules responsible for causing insulin resistance." (PMID 21274300, 2009). "Moreover, excessive NF-κB activity has been associated with the development of type 2 diabetes as obese individuals have high circulating levels of TNF-α, IL-1β and IL-6 that, like cardiovascular risk, directly correlate with insulin resistance." (PMID 18549505, 2008). "Interestingly, TNF-α seems to be responsible for the insulin-resistance associated with obesity, since decreases the tyrosine kinase activity of the insulin receptor." (PMID 17971205, 2007).
Insulin resistance (continued). "By inducing insulin resistance TNF-α may cause metabolic disturbances associated with increased cardiovascular risk, such as low HDL cholesterol levels, hypertriglyceridemia and impaired fibrinolysis." (PMID 23675033, 2007). "We hypothesised that short-term glucocorticoid treatment among healthy individuals would cause insulin resistance, with coordinated increases in TNF alpha, leptin and ghrelin, and decreases in adiponectin." (PMID 16965635, 2006). "The negative correlation between serum resistin and adiponectin levels may also suggest that, resistin could be a marker for TNF-α which has been shown to be associated with chronic inflammation and insulin resistance." (PMID 16669997, 2006). "Central insulin resistance may lead to the risk of cardiometabolic syndrome through the increase of inflammatory markers (TNF-alpha and PAI-1), treated with gliquidone, in 50 patients with cancer infected with COVID-19, who were dependent on developing immunothrombosis." (PMID 40599143, 2025). "Moreover, systemic inflammatory markers, such as tumor necrosis factor-α and interleukin-1β, which trigger c-Jun N-terminal kinases and IκB kinase β/Nuclear Factor Kappa B pathways, are linked to insulin resistance, potentially fostering atherosclerosis and vascular remodeling." (PMID 39941621, 2025). "Hence, in this study, we aimed to conduct a comparative analysis of the effects of TNFα, LPS, and PA or their combination effects on mitochondrial dysfunction and associated metabolic complications including oxidative stress damage and insulin resistance in cultured 3T3-L1 adipocytes." (PMID 39269560, 2025). "In addition, chronic stress triggers the release of pro-inflammatory cytokines, including interleukin-6 and tumor necrosis factor-alpha, which increase insulin resistance and cause chronic low-grade inflammation, contributing to oxidative stress and subsequent liver injury." (PMID 41196923, 2025). "Research has found a close association between low‐grade chronic inflammation and insulin resistance, suggesting that OS may contribute to this chronic inflammation, where inflammatory mediators such as TNF‐α and IL‐6 exacerbate the pathological state of insulin resistance." (PMID 40599237, 2025). "In addition, TNFα may be associated with sarcopenia by promoting insulin resistance, delaying muscle repair, and exacerbating the pro-inflammatory response by up-regulating IL-6." (PMID 38732615, 2024). "Similarly, TNF-α, a multifunctional pro-inflammatory cytokine produced by adipose tissue, and IL-6, another major pro-inflammatory marker, are linked to various health implications including insulin resistance, neurodegeneration, and cancer." (PMID 38999799, 2024). "However, an increase in central obesity also influences muscle quality through insulin resistance and an increase in pro-inflammatory cytokines, such as tumor necrosis factor-alpha and interleukin-6, which are associated with lower muscle strength and physical function." (PMID 39184798, 2024). "In addition, several studies have demonstrated that sarcopenia was associated with insulin resistance, vitamin D deficiency, elevated levels of inflammatory cytokines (such as tumor necrosis factor-alpha and interleukin-6), and decreased concentrations of muscle factors (such as interleukin-15)." (PMID 38287345, 2024). "Abnormal FPG concentrations and the risk of insulin resistance related to TNF-α may involve the generation of reactive oxygen species and impairment of insulin signaling through serine phosphorylation, which leads to the development of type 2 diabetes mellitus." (PMID 38542788, 2024). "Therefore, the IL-6 mediated suppression of TNF-alpha, as a product of regular exercise, offers protection against inflammation and may also lead to the reduction in TNF-alpha-associated insulin resistance." (PMID 37227593, 2023). "Thus, COPD patients are at high risk of developing insulin resistance via a TNF-α-mediated pathway." (PMID 37238649, 2023).
Insulin resistance (continued). "Moreover, neuronal insulin resistance is also associated with neuroinflammation via the tumor necrosis factor-α (TNFα) /c-Jun N-terminal kinases (JNK) pathway, which, in AD, is activated by Aβ oligomers and misfolded Tau that consequently alter the IRS1/mTOR signaling pathway." (PMID 36875654, 2023). "In addition, neutralization of TNFα significantly increased insulin-stimulated peripheral uptake of glucose, a result that demonstrates a strong association between higher TNFα levels and insulin resistance." (PMID 37935669, 2023). "Insulin resistance, which remains a major metabolic abnormality in the great majority of patients with Type 2 diabetes, is caused by altered functions within the insulin target cells and the accumulation of macrophages secreting proinflammatory mediators, such as IL-6, TNFα, IL-8, and MCP-1." (PMID 36015180, 2022). "Pro-inflammatory cytokines such as CRP, interleukin-6 (IL-6) and tumour necrosis factor alpha (TNF-α) are derived from immune cells or adipocytes and are implicated in inhibiting the insulin signalling cascade whilst also positively associated with insulin resistance." (PMID 36145067, 2022). "In addition, TNF-α has been linked to β cell dysfunction and insulin resistance." (PMID 35741012, 2022). "Moreover, IP-10 levels were associated with MCP-1, TNF-α, and insulin resistance." (PMID 36552805, 2022). "Interestingly, HFD directly stimulates TLR4/ NF-κB signaling, leading to increased local inflammation through upregulation of TNF-α, which may contribute to low-grade systemic inflammation associated with insulin resistance." (PMID 36329549, 2022). "In addition, P. gingivalis LPS is possibly implicated in insulin resistance, either by stimulating the activation of pro-inflammatory cytokines such as TNF-α and IL-6, which play important roles in insulin resistance, or by directly inhibiting glucose incorporation into smooth muscle cells." (PMID 35308549, 2022). "In addition, the low-grade of inflammation associated with the situation of insulin resistance results in an enhanced production and secretion of pro-inflammatory mediators (tumor necrosis factor [TNF]-α, interleukin [IL]-6, etc.)that in turn inhibits the insulin signaling pathway." (PMID 34208379, 2021). "The pathophysiological hypothesis underlying this epidemiological association seems to be the development of insulin resistance in hypothyroidism, probably through increased oxidative stress, lipid peroxidation and the rise of several adipocytokines such as leptin and tumor necrosis factor α (TNFα)." (PMID 34884625, 2021). "Additionally, systemic inflammation plays an important role in the pathogenesis of prediabetes and T2DM, given that the adipose tissue can overproduce pro-inflammatory cytokines like TNF-α, which impairs insulin signalling, increasing the risk of insulin resistance." (PMID 33578998, 2021). "This is consistent with the rise in plasma TNFα and IL-6 emanating mostly from NF-κB activation in endothelial cells without involving adipokines released from adipose tissue macrophages that are typically associated with systemic insulin resistance and visceral obesity." (PMID 34440862, 2021). "We then investigated whether DHM improved insulin resistance caused by TNF‐α." (PMID 34676967, 2021). "TNF-α could cause muscle cell inflammation and lead to insulin resistance." (PMID 34003397, 2021). "Although it is not fully understood whether inflammatory cytokines are a cause of insulin resistance or are purely markers of dysfunctional adipose tissue, plasma levels of several cytokines including TNF-α, IL-6 and adiponectin are independent predictors of T2D." (PMID 33322261, 2020). "The underlying mechanism for TNF-driven atherothrombosis could be via a variety of proposed mechanisms, including favourable effects on circul1ating lipids, insulin resistance, endothelial dysfunction, leucocyte recruitment, oxidative stress, vasodilation or coagulation." (PMID 32805626, 2020).
Insulin resistance (continued). "In addition, cytokines (TNF-α, IL-6, and IL-1β) may play a role in the hepatic and systemic insulin resistance associated with NASH." (PMID 32316419, 2020). "Moreover, ferritin as an inflammatory factor is connected with interleukin 6 and tumor necrosis factor alpha, which, in turn, may cause insulin resistance." (PMID 31969861, 2019). "In addition, it has been proposed that cytokines involved in the pathogenesis of psoriasis (e.g., TNF-α and IL-17) may also affect glucose metabolism, possibly promoting insulin resistance and thereby increasing the risk of CVD in these patients." (PMID 30735527, 2019). "Thus, even low concentrations of circulating TNFα might represent a risk factor for vascular insulin resistance in elderly people." (PMID 31013778, 2019). "Thus, the observed increase in TNF-α in mPGES-1-deficient mice might contribute to the enhanced insulin resistance." (PMID 30382148, 2018). "TNF-α is secreted by macrophages presented on stromal vascular tissue from adipose tissue and represents a pro-inflammatory adipokine, providing a central role in insulin resistance, causing the phosphorylation of the substrate-1 of the insulin receptor, and avoiding its pairing." (PMID 29497960, 2018). "Among RA-related risk factors, proinflammatory cytokines (TNF-α, IL-6), oxidative stress, an increase of leptin and resistin (proatherogenic hormones) and the decrease of adiponectin (antiatherogenic hormone), and insulin resistance play the most important role in accelerated atherogenesis." (PMID 29200598, 2017). "TNF-α is also implicated in peripheral insulin resistance in diabetes, and it has been proposed that neuronal insulin resistance induced by TNF-α may underlie the connection between diabetes and AD." (PMID 28197094, 2017). "Therefore, increased TNF-α causes the development of insulin resistance in skeletal muscle and WAT." (PMID 28168013, 2017). "Indeed, inflammatory M1 macrophages infiltrating the obese WAT produce proinflammatory mediators (TNF-α, IL-1β, IL-6), which are associated with the development of insulin resistance and the subsequent release of NEFA, leading to systemic lipotoxicity, with effects on the liver and kidney." (PMID 28188334, 2017). "Since resistin and TNF-α are pro-inflammatory in action, and inflammation has a central role in cardiovascular diseases and insulin resistance, deficiency of vitamin B12 may, therefore, have importance in the development of cardiometabolic diseases in Saudi population." (PMID 27608037, 2016). "It is well known that inflammatory cytokines TNFα and IL-6 could cause insulin resistance." (PMID 26938554, 2016). "Therefore, the fourth limitation is that we did not measure other cytokines, such as leptin, adiponectin, IL-6 and TNF-α, which may be related to serum irisin level and may confound the association between irisin and insulin resistance." (PMID 27473122, 2016). "Notably, LPS or TNF-α treatment also upregulated Wnt5a expression in adipocytes, indicating that adipocyte-derived Wnt5a is also implicated in adipose tissue inflammation and insulin resistance." (PMID 27608847, 2016). "However, the reduction of NF-κB by oleate might be implicated in the protective role of oleate against insulin resistance induced by the TNF-α or palmitate." (PMID 26055507, 2015). "Furthermore, many studies suggested that TNFα is one of the major causes of insulin resistance." (PMID 26576191, 2015). "In addition, increased TNF-α levels were predominantly associated with insulin resistance." (PMID 25105150, 2014). "TNF-α and IL-6 are potent inhibitors of adiponectin expression and secretion in WAT biopsies and culture cells, suggesting that insulin resistance induction by TNF-α and IL-6 may also be caused by an inhibition of the autocrine-paracrine liberation of adiponectin." (PMID 24741627, 2014).
Insulin resistance (continued). "Since elevated inflammatory factors were closely associated with impaired glucose tolerance and insulin resistance, we assessed the expression of TNF-α and IL-6 to investigate whether changes in inflammatory status could link the maternal HFolS to insulin resistance." (PMID 24736781, 2014). "In addition, TNF-α causes insulin resistance through attenuation of IR signaling." (PMID 24481061, 2014). "Thus, in the present study, improvement of insulin resistance by the AI extract might be associated with decreased gene expression and/or production of cytokines such as TNFα, IL-6, MCP1, and leptin." (PMID 23401719, 2013). "The rise in TNF-α levels may be related to pregnancy-associated increases insulin resistance." (PMID 23691290, 2013). "A-FABP-deficient mice exhibited reduced hyperinsulinemia and insulin resistance in the context of both dietary and genetic obesity, which might be caused by decreased TNF-alpha expression, enhanced insulin receptor signaling and muscle AMP-activated kinase activity." (PMID 23375099, 2013). "Besides, TNF-α inhibits adiponectin expression, causes elevation in serum free fat acid by stimulation of lipolysis and hepatic lipogenesis, contributing for insulin resistance and may lead to development of NAFLD, justifying our findings." (PMID 23919592, 2013). "An alternative mechanism could be via TNF-α, which is known to cause insulin resistance." (PMID 22615949, 2012). "However, this evidence brings to question whether in TNF-α is a causative link between adiposity and insulin resistance." (PMID 22523672, 2012). "In addition, chronic magnesium deficiency has also been associated with elevated concentrations of TNF-alpha, and this fact may also contribute to post-receptor insulin resistance." (PMID 22291997, 2012). "Collectively, these findings demonstrate that TXA mitigates TNF-α-induced insulin resistance by improving insulin signaling, suppressing inflammation and oxidative stress, and improving lipid and mitochondrial metabolism." (PMID 41835598, 2026). "High VAT content promotes inflammation and tumor progression via cytokine secretion (leptin, resistin, IL-6, and TNF- α), angiogenesis, and insulin resistance." (PMID 40699302, 2026). "T2D similarly represents a chronic low‐grade inflammatory state, with TNF‐α and IL‐6 potentially driving worsening insulin resistance and β‐cell dysfunction." (PMID 41388732, 2026). "Excess visceral adipose tissue is infiltrated by macrophages, which secrete TNF-α and IL-6, which serve to enhance insulin resistance by modulating the signaling of insulin through peripheral tissues, thus sustaining a pro-diabetogenic vicious circle." (PMID 41590667, 2026). "Elevated maternal TNF-α correlates positively with fasting glucose and homeostatic model assessment of insulin resistance (HOMA-IR)." (PMID 41596503, 2026). "In vitro studies have documented that IL‐10 protects against TNF‐α‐dependent insulin resistance in adipocytes." (PMID 41549047, 2026). "TNF-α, a major driver of hepatic inflammation and insulin resistance, decreased by 53.2% (P < 0.001; d = 2.1), highlighting the anti-inflammatory effects of both weight loss and dietary quality improvement." (PMID 40988029, 2025). "Elevated TNF-α levels, in turn, can exacerbate insulin resistance and contribute to the chronic low-grade inflammation observed in T2DM." (PMID 41268160, 2025). "Conversely, adipocytokines TNFα and resistin, which have been shown to contribute to insulin resistance, had their mRNA levels downregulated by repeated palmitoleic acid delivery." (PMID 39940428, 2025). "TNF-α promotes inflammation and insulin resistance by influencing the MAPK and NF-κB signaling pathways and IRS-1 phosphorylation." (PMID 40362446, 2025). "Another study reported elevated CER concentrations in diabetes patients compared to healthy controls, which correlated with greater insulin resistance and higher levels of inflammatory marker TNF-α levels." (PMID 41286497, 2025).